EP300 (EP300 lysine acetyltransferase)
Diseases named in the same sentence as EP300 in open-access papers (continued):
Sharing a sentence is not in itself a finding about the gene and the disease.
spina bifida (2 papers, 2010 to 2019). A congenital neural tube defect in which vertebrae are not fully formed. "A case–control study, including 297 spina bifida cases and 300 controls, found 37 SNPs within EP300 and CREBBP were associated with the occurrence of spina bifida." (PMID 31612645, 2019). "The purpose of this study is to evaluate the potential association between variations among human CITED2, CREBBP, EP300, TFAP2A, CARM1 and ALX1 genes and the risk for spina bifida." (PMID 20932315, 2010). "We have observed modest associations with risk of spina bifida in CITED2, EP300, CREBBP, TFAP2A and CARM1 genes but not ALX1 gene." (PMID 20932315, 2010).
adenoid cystic carcinoma (1 paper, 2023). A malignant tumor arising from the epithelial cells. "In particular, we found that the site of the P10 tripeptide in EP300 sequence is involved in an EP300 truncating mutation, N1307Efs* 2, detected in adenoid cystic carcinoma tumors." (PMID 37954147, 2023).
adrenocortical carcinoma (1 paper, 2020). "We had a 2-year-old male patient with adrenocortical carcinoma who had three P/LP KCPG variants in NTRK1, EP300, and HMBS genes." (PMID 32371905, 2020).
adult T-cell leukemia/lymphoma (1 paper, 2025). A peripheral (mature) T-cell neoplasm linked to the human T-cell leukemia virus type 1 (HTLV-1), adult T-cell leukemia/lymphoma is endemic in several regions of the world, in particular Japan, the Caribbean, and parts of Central Africa. "In this study, four North American Adult T-cell leukemia/lymphoma (NA-ATLL) patient-derived cell lines were analyzed, which included two EP300 wildtype (NA1, NA4) and two EP300 mutants (NA2 and NA3)." (PMID 41354653, 2025).
amyloid (1 paper, 2024). "Our study uncovers a novel link between EP300/CBP and amyloid pathology in AD." (PMID 38167174, 2024).
Aortic dissection (1 paper, 2022). Aortic dissection refers to a tear in the intimal layer of the aorta causing a separation between the intima and the medial layers of the aorta. "New genes (MLX, DAB2IP, EP300, ZFYVE9, PML, PRKCD) were suggested as candidate aortic dissection-associated genes, through correlation analyses performed on the results of a WES study on a cohort of 99 Chinese cases." (PMID 35892496, 2022).
B-cell neoplasm (1 paper, 2025). A group of heterogeneous lymphoid tumors generally expressing one or more B-cell antigens or representing malignant transformations of B-lymphocytes. "In the murine B-cell neoplasms example, the cases with chromatin-modifying gene CREBBP or EP300 mutations that had a decreased H3K27 acetylation led to higher M2 polarization and a faster tumor progression when compared to CREBBP/EP300 wild-type, regulated via the FBXW7-NOTCH-CCL2/CSF1 axis." (PMID 40426926, 2025).
cardiac septal defect (1 paper, 2009). "Of these, 3 genes (SRF, EP300, and CREBBP) have been associated with cardiac septal defect." (PMID 19245720, 2009).
cervix (1 paper, 2021). "We found that CREBBP/EP300 mutations were associated with poorer overall survival in radiation-treated patients with lung and cervix squamous tumors." (PMID 34732714, 2021).
ciliopathy (1 paper, 2022). A genetic disorder of the cellular cilia or the cilia anchoring structures, the basal bodies, or of ciliary function. "The targets of CREBP1 found from among the genes shared between the HLHS and ciliopathy interactomes were EP300, PRNP, SMAD3, SUMO1 and TBX6, while the targets of ALX4 were JUN and TCF7L2." (PMID 35456433, 2022). "Eight direct known interactions were found between HLHS candidates and ciliopathy-associated genes (HLHS candidates are shown in bold): TSC22D1-UNC119, RPTOR-CILK1, MFSD6-TMEM237, EP300-CRX, CTNNA3-CRX, CTNNA3-FAM161A, NIF3L1-NME7 and TSC1-GLIS2, and one direct novel interaction, RPTOR-CCDC40." (PMID 35456433, 2022).
ductal adenocarcinoma (1 paper, 2024). "In ductal adenocarcinoma of the breast, FOXA1, together with EP300 and RUNX1, enhances E-cadherin promoter activity in metastatic breast cancer cells." (PMID 38605023, 2024).
Dupuytren’s disease (1 paper, 2020). "Interestingly, EP300 showed a distinct binding profile closely localizing with 8 of the 22 most significant SNPs associated with Dupuytren’s disease." (PMID 32759223, 2020).
endocervical carcinoma (1 paper, 2019). A carcinoma that arises from epithelial cells of the endocervix. "For example, mutation of EP300 was associated with differences in expression of cell cycle and JAK-STAT pathways in bladder, endometrial, cervical and endocervical cancers." (PMID 30803482, 2019).
familial cancers (1 paper, 2021).
hyperthyroidism (1 paper, 2021). Overactivity of the thyroid gland resulting in overproduction of thyroid hormone and increased metabolic rate. "A total of 112 genes related to R. Scrophulariae and hyperthyroidism were obtained, and these included PTEN, EP300, and CCNB1." (PMID 34650432, 2021).
Hypoinsulinemia (1 paper, 2025). A decreased concentration of insulin in the blood. "Lack of EP300 expression in islet cells can lead to a decrease in the number of pancreatic α and β cells and then cause hypoinsulinemia." (PMID 40508108, 2025).
influenza (1 paper, 2024). An acute viral infection of the respiratory tract, occurring in isolated cases, in epidemics, or in pandemics; it is caused by serologically different strains of viruses (influenzaviruses) designated A, B, and C, has a 3-day incubation period, and usually lasts for 3 to 10 days. "Similarly, hsa-miR-5003-3p, EP300, Valproic Acid, Influenza, and ELAVL1 have interactive relationships centered around EIF2AK2, while hsa-miR-6893-3p, EP300, Calcitriol, Influenza, and HNRNPA2B1 exhibit interactive relationships centered around OASL." (PMID 38601162, 2024).
kidney cancer (1 paper, 2021). Primary or metastatic malignant neoplasm involving the kidney. "However, KAT2A was not significantly up-regulated in 800 samples based on GEO and EBI database, and EP300 was significantly up-regulated in kidney cancer, PRAD and TGCT." (PMID 34136387, 2021).
lentivirus infection (1 paper, 2023). Virus diseases caused by the Lentivirus genus. "EP300-wt and EP300-R1627W were reintroduced into T24-EP300kd cells using lentivirus infection." (PMID 36647005, 2023).
macrosomia (1 paper, 2015). "Expression levels of SMAD4, SMAD3, RB1 and EP300 genes were significantly decreased in placentas of neonates with macrosomia compared with those of controls." (PMID 26598317, 2015).
MALT lymphoma (1 paper, 2021). An indolent, extranodal type of non-Hodgkin lymphoma composed of small B-lymphocytes (centrocyte-like cells). "Inactivation of chromatin remodeling genes are frequently observed in MALT lymphomas, with the most common mutated genes being TET2, KMT2D, CREBBP, TBL1X1, KMT2C, MT2C, EP300, among others." (PMID 35008340, 2021).
Menke-Hennekam syndrome 2 (1 paper, 2023). A form of Menke-Hennekam syndrome, a congenital autosomal dominant disease characterized by developmental delay, growth retardation, and craniofacial dysmorphism. "Mutations in the EP300 gene can lead to Menke-Hennekam syndrome-2 (MKHK2), characterized by variable impairment of intellectual development and facial dysmorphisms." (PMID 37035742, 2023).
Miscarriage (1 paper, 2024). A pregnancy that ends at a stage in which the fetus is incapable of surviving on its own, defined as the spontaneous loss of a fetus before the 22th week of pregnancy.
mitral atresia (1 paper, 2025). "Patients in Group 2, the mitral atresia group, carried variants in the genes including EP300, NOTCH1, and TTN (mitral atresia), CREBBP, EP300, and NOTCH1 (hypoplastic left ventricle)." (PMID 41153298, 2025). "Patients in Group 2, the mitral atresia group, carried variants in genes related to mitral atresia, including EP300, NOTCH1, and TTN." (PMID 41153298, 2025).
Myalgia (1 paper, 2025). "However, central in this core net one can find the genes NF2 and BRAF (associated to HPO-class BN and ACTH), EP300 (associated to HPO-class BN), AAAS (associated to HPO-class ACTH) and PTPN2 (associated to Myalgia)." (PMID 40831500, 2025).
oropharyngeal squamous cell carcinomas (1 paper, 2020). "Just recently an association of EP300 mutations and intragenic EP300 deletions were discovered for HPV-positive oropharyngeal squamous cell carcinomas in two independent studies." (PMID 32523042, 2020).
osteonecrosis (1 paper, 2024). A none disease characterized by death of bone tissue due to a lack of blood supply. "EP300, TRAF6, STAT1, JAK1, CASP8, and JAK2 have exhibited significant differences in SANFH (spontaneous osteonecrosis of the femoral head)." (PMID 38204239, 2024). "In conclusion, EP300, TRAF6, STAT1, JAK1, CASP8, and JAK2 exhibit significant differences in SANFH (spontaneous osteonecrosis of the femoral head)." (PMID 38204239, 2024).
pilomatrixoma (1 paper, 2015). Pilomatrixoma is a rare and benign hair cell-derived tumor occurring mostly in young adults (usually under the age of 20) and characterized as a 3-30 mm solitary, painless, firm, mobile, deep dermal or subcutaneous tumor, most commonly found in the head, neck or upper extremities. "A less strict follow-up protocol may be only appropriate for RSTS patients with EP300 mutations, with focus on skin problems (pilomatrixomas and nevi) that are likely more frequent than in patients with CREBBP mutations." (PMID 25599811, 2015).
primary immunodeficiencies (1 paper, 2018). "WES revealed heterogeneous genetic background among CVID patients with tumors, identifying gene variants associated with primary immunodeficiencies (such as CTLA4, PIK3CD, PMS2) and/or increased cancer susceptibility (including BRCA1, RABEP1, EP300, KDM5A)." (PMID 30723478, 2018).
prostate adenocarcinoma (1 paper, 2021). "We found that multiple CNVs, both gains and losses, affected EP300 and CBP in liver hepatocellular carcinoma (LIHC) and prostate adenocarcinoma (PRAD) and correlated with their expression." (PMID 33602823, 2021).
psychosis (1 paper, 2021). "Then, we explored the genetically predicted EP300 expression levels in a cohort of 226 patients with first-episode psychosis who were being treated with APs to further assess the association of this gene with metabolic alterations." (PMID 34483940, 2021).
rectal tumor (1 paper, 2017). "Re-biopsy of the rectal tumor was obtained to assess for mechanisms of resistance and sequencing identified FGFR1 and EGFR gene amplifications; and an E1A binding protein p300 (EP300) mutation in codon L1755V, and a Wolf-Hirschhorn Syndrome Candidate 1-Like 1 (WHSC1L1) mutation in codon E123Q." (PMID 28915719, 2017).
Right ventricular hypertrophy (1 paper, 2023). In this case the right ventricle is more muscular than normal, causing a characteristic boot-shaped (coeur-en-sabot) appearance as seen on anterior- posterior chest x-rays. "Knockdown of EP300 by AAV-mediated shRNA exacerbated the PH, with a higher right ventricular systolic pressure (RVSP), right ventricular hypertrophy index (RVHI), and wall thickness in the pulmonary artery of MCT-induced PH rat." (PMID 36910531, 2023).
small-bowel cancer (1 paper, 2021).
T-cell lymphoma (1 paper, 2021). "For T-cell lymphoma six genes are found in cosmic (JAK1, PLCG1, FYN, ARID1A, EP300, and MAP3K1), and 13 are known oncogenes." (PMID 34570764, 2021).
viral myocarditis (1 paper, 2024). Myocarditis that is caused by an infection with a viral agent. "EP300, a crucial target of glycosides, impacts viral myocarditis, chemotaxis of monocytes and macrophages, and T-cell activation, leading to antibody responses, potentially serving as a therapeutic target for influenza A viruses." (PMID 38601162, 2024).
cancer (530 papers, 2006 to 2026). A tumor composed of atypical neoplastic, often pleomorphic cells that invade other tissues. "It has been reported that the EP300 protein, an enzyme encoded by the EP300 gene, plays a role in regulatory T-cell function and is expected to be used in possible cancer immunotherapy." (PMID 40900757, 2025). "Additional cooperating mutations in known cancer genes (including Nf1, Ep300, Notch1, Sbds, and Ets1) were identified in 5 of the 9 GAB2 mAMLs." (PMID 40773291, 2025). "The overall rarity of CREBBP and EP300 mutations, however, restricts interpretation for individual cancer types." (PMID 41301688, 2025). "Here, the authors reveal that the EP300 protein has a role in mediating replication fork protection at sites of replication stalling and show that EP300-mutated cells recapitulate features of BRCA-deficient cancers." (PMID 41354653, 2025). "Overall, these findings pave the way towards evaluating novel therapeutic strategies for EP300-mutated cancers such as ATLL." (PMID 41354653, 2025). "There is currently a keen interest in understanding the potential mechanisms underlying EP300 mutation-related tumorigenesis and their overall implications for cancer therapy." (PMID 41354653, 2025). "Several well-known cancer-associated genes (e.g. EP300, FAT1) have carcinogenic effect estimates in the statistical vicinity of one, yet they also exhibit strong signals of positive selection in ESSCs17." (PMID 41279109, 2025). "Histone acetyltransferase of EP300 was strongly associated with the progression of bladder cancer, breast cancer, lung cancer, and some kinds of other cancers." (PMID 38835125, 2024). "In the present study, we show that simultaneous inhibition of two genes (CREBBP + EP300) causes synthetic lethality in cancers with a LOF mutation in another gene (i.e., SMARCB1)." (PMID 38839769, 2024). "It suggested that H3K27ac tend to aggravate the cancer biology of EP300 mutations though other mechanisms like enhancer-hijacking." (PMID 37876590, 2023). "Aberrant expression of CREBBP/EP300 causes Rubinstein–Taybi syndrome and multiple hematologic malignancies by losing their activity." (PMID 36831561, 2023). "The loss of Wnt/β-catenin activity seen in the existing RNF43/EP300-mutant cancer cell lines is likely due to the loss of any selective pressure to maintain Wnt signaling in these cells once p300 is mutated." (PMID 35536676, 2022). "The mutations of EP300 in cancer encompass microdeletions, truncating mutations, and point mutations in different domains and occurred in 30 of 379 ENKTL cases (7.9%) examined by NGS." (PMID 35054466, 2022). "We also investigated the association between EP300 mutations and antitumor immune activity in these cancer types." (PMID 34616736, 2021). "Taken together, these results indicate a significant association between EP300 mutations and genome instability in cancer." (PMID 34616736, 2021). "Our data also showed that EP300 mutations were correlated with DDR deficiency, such as a high proportion of MSI cancers in the EP300-mutated subtype and co-mutation of EP300 with DNA mismatch repair and DDR pathway genes." (PMID 34616736, 2021). "Through mouse genetics and human tumor sequencing analyses, EP300 has been widely associated with cancers and other pathological conditions." (PMID 34149798, 2021). "The EP300 mutation correlates with heightened genome instability, antitumor immune activity, and immunotherapeutic response in cancer." (PMID 34616736, 2021). "Based on its loss in several types of cancer, EP300 was suggested to behave as a tumor suppressor gene." (PMID 33602823, 2021). "For example, the ratios of M1/M2 macrophages were significantly higher in EP300-mutated than those in EP300-wild-type cancers in BLCA, HNSC, CESC, STAD, and ESCA; the permutation test showed that this finding was significant (p < 0.0001)." (PMID 34616736, 2021).